BRCA2 (BRCA2 DNA repair associated)
Diseases named in the same sentence as BRCA2 in open-access papers (continued):
Sharing a sentence is not in itself a finding about the gene and the disease.
breast cancer (continued). "The majority of hereditary breast cancer (HBC) susceptibility can be attributed to germline mutations of to Breast Cancer 1 and Breast Cancer 2 genes (BRCA1 and BRCA2), which are responsible for 30-40% of HBC." (PMID 23217244, 2012). "Cases (n=60) included 3 BRCA1 and 25 BRCA2 mutation carries, and 32 non-BRCA1/2 (BRCAX) carriers with strong family histories of breast cancer." (PMID 23146383, 2012). "This correlation was found to be in the opposite direction in the normal tissue of breast cancer patients, with lower SPP1 expression associated with a low BRCA2 expression haplotype (P-value = 0.038)." (PMID 22513257, 2012). "Although hereditary breast cancer is responsible for about 5–10% of all breast cancers, women carrying BRCA1 and BRCA2 gene mutations have especially high risk of breast cancer development." (PMID 22382806, 2012). "Relationship between duration of breastfeeding and risk of breast cancer among BRCA1 and BRCA2 mutation carriers." (PMID 22405187, 2012). "Germline mutations in the BRCA1 (MIM# 113705) and BRCA2 (MIM# 600185) genes confer a high lifetime risk of developing breast/ovarian cancer and account for about 16% of the breast cancer familial risk." (PMID 22632462, 2012). "BRCA1 is mutated more frequently in families with both breast and ovarian cancer and more rarely in families with male breast cancer where BRCA2 is predominant." (PMID 22290208, 2012). "In this study, we focused on 2 previously reported canine BRCA2 mutations (T1425P and K1435R) in BRC repeat 3 (BRC3), derived from mammary tumor samples." (PMID 23071527, 2012). "Patients with early onset breast cancer had a variety of BRCA1 and BRCA2 mutations based on the combined risk groups." (PMID 22382806, 2012). "In our ongoing study of breast cancer predisposition genes in a hospital-based cohort of breast cancer patients, we have analyzed BRCA1 and BRCA2 in all patients younger than 35 years diagnosed with invasive breast cancer." (PMID 22507745, 2012). "So far, while BRCA2, BRIP1, PALB2, and RAD51C are associated with high or moderate breast cancer risk, the impact of SLX4 on breast cancer remains to be measured." (PMID 22383991, 2012). "Both these genes work in a similar way as BRCA1 and BRCA2, and this highlights the importance of these functions in preventing breast cancer." (PMID 23028338, 2012). "Genomic DNA from probands of 44 Ashkenazi Jewish high-risk breast cancer families (wild-type for BRCA1, BRCA2 and CHEK2) was sequenced." (PMID 22347400, 2012). "At present, the most frequent indications for bilateral risk-reducing mastectomy are high risk histology (such as a typical ductal or lobular hyperplasia and lobular carcinoma in situ), strong family history and positive mutation in the BRCA1 or BRCA2 genes." (PMID 22503188, 2012). "The multivariate odds ratio for contralateral breast cancer associated with tamoxifen use was 0.50 for carriers of BRCA1 mutations (95% CI, 0.30–0.85) and 0.42 for carriers of BRCA2 mutations (95% CI, 0.17–1.02)." (PMID 22312502, 2011). "A significant proportion of individuals with hereditary breast cancer have mutations in the tumor suppressor genes BRCA1 (OMIM # 113705) and BRCA2 (OMIM # 600185)." (PMID 22185575, 2011).
breast cancer (continued). "Breast cancer risks for BRCA1 and BRCA2 mutation carriers have been estimated to range between 40 and 87% by age 70 with population-based estimates tending to be lower than estimates based on families with multiple affected individuals." (PMID 22053997, 2011). "The human breast cancer suppressor protein BRCA2 controls the functions of the RAD51 recombinase, an enzyme conserved in all kingdoms of life, which carries out the strand exchange reaction central to homologous DNA recombination (HDR)." (PMID 21789034, 2011). "While studies have identified low-penetrance alleles that associate with breast cancer risk in carriers of BRCA1 mutations and carriers of BRCA2 mutations, specificities have also been detected." (PMID 22110403, 2011). "The breast cancer suppressor BRCA2 controls the recombinase RAD51 in the reactions that mediate homologous DNA recombination, an essential cellular process required for the error-free repair of DNA double-stranded breaks." (PMID 21789034, 2011). "Here, we explore the relationships between the MSA and the Rad51 gene, which encodes a DNA repair enzyme that interacts with BRCA1 and BRCA2, in BRCA1 mutation carriers and women with sporadic breast cancer." (PMID 21708019, 2011). "This is the first report to investigate the associations between 12 common breast cancer susceptibility alleles and ER and PR status of breast tumours in BRCA1 and BRCA2 mutation carriers." (PMID 22053997, 2011). "Mutations in two genes that were initially identified as predisposing carriers to early-onset breast cancer, BRCA1 and BRCA2, cause similar perturbations in cellular responses to DNA damage but predispose carriers to distinct tumor types." (PMID 22110403, 2011). "The breast cancer suppressor BRCA2 is essential for the maintenance of genomic integrity in mammalian cells through its role in DNA repair by homologous recombination (HR)." (PMID 22194698, 2011). "The two major high-penetrance BrCa genes, BRCA1 (breast cancer 1) and BRCA2 (breast cancer 2), are responsible for 30% of hereditary breast cancer (HBC) cases worldwide, but only for about 20% in Finland." (PMID 21356067, 2011). "Mastectomy has long been proposed as a means of avoiding breast cancer in women with BRCA1 and BRCA2 mutations." (PMID 22312537, 2011). "The NCCN recommends that breast cancer screening for BRCA1- and BRCA2-mutation carriers should include annual mammography and clinical breast examination every 6–12 months, starting at age 25 or individualized based on one's family history." (PMID 22312502, 2011). "BRCA1 and BRCA2 mutations are quite penetrating: the cumulative risk of breast cancer is about 65% in BRCA1-mutation carriers (by age 70) and about 45% in BRCA2-mutation carriers." (PMID 22312537, 2011). "W31C mutation, which is annotated in the Breast Cancer Information Core (BIC) database, impairs the interaction of full-length BRCA2 with PALB2 and impairs HR function." (PMID 22194698, 2011). "The risk of developing breast cancer by the age of 70 for carriers of BRCA1 is 57% to 65%, while the risk in BRCA2 carriers is slightly lower, at 45% to 49%, based on the findings of two recent metaanalyses." (PMID 22295226, 2011). "Five-to-ten percent of breast cancers occur in women with a deleterious mutation in BRCA1, BRCA2, or other breast cancer-associated genes." (PMID 22312537, 2011). "Currently known susceptibility genes including BRCA1, BRCA2, ATM, CHEK2, PALB2, RAD51C and BRIP1 explain less than 25% of familial breast cancer." (PMID 21774837, 2011).
breast cancer (continued). "Many of the genes already associated with breast cancer susceptibility encode proteins that operate together with BRCA1 and BRCA2 in the DNA damage response pathway (DDR)." (PMID 21774837, 2011). "It was concluded that tamoxifen reduced breast cancer incidence among BRCA2 carriers by 62%, similar to the reduction of ER+ breast cancer among all women in the breast cancer prevention trial." (PMID 22312502, 2011). "Patients were 810 women, with stage I or II breast cancer, for whom a BRCA1 or BRCA2 mutation had been identified in the family." (PMID 21487411, 2011). "The sample sizes for tumour subtypes, while still large, were, therefore, much smaller than were available for analyses of breast cancer risk overall, particularly for ER-positive breast cancer in BRCA1 carriers and ER-negative breast cancer in BRCA2 carriers." (PMID 22053997, 2011). "Women with a known family history of breast cancer, or of a predisposing gene mutation such as BRCA1 or BRCA2, have a cumulative lifetime risk of 45–65%, and a significant number of these cancers are diagnosed before the age of 50 years." (PMID 21326245, 2011). "Genomic analysis of BRCA1 and BRCA2 for 288 women who developed breast cancer was completed after entry into the trial." (PMID 22312502, 2011). "The objective of this study was to estimate the risk of contralateral breast cancer in BRCA1 and BRCA2 carriers; and measure the extent to which host, family history, and cancer treatment-related factors modify the risk." (PMID 21487411, 2011). "Then, it seems that hereditary breast cancer is associated with short telomeres, especially in BRCA1 and BRCA2 mutation carriers, as well as in a subgroup of BRCAX." (PMID 21829373, 2011). "Previous studies have demonstrated that common breast cancer susceptibility alleles are differentially associated with breast cancer risk for BRCA1 and/or BRCA2 mutation carriers." (PMID 22053997, 2011). "Women suffering from breast cancer, showing mutations on the BRCA1 and BRCA2 genes, apparently are more susceptible to present genetic damage in others tissues than healthy individuals." (PMID 21556202, 2011). "The 15-year actuarial risk of contralateral breast cancer was 36.1% for women with a BRCA1 mutation and was 28.5% for women with a BRCA2 mutation." (PMID 21487411, 2011). "The cumulative breast cancer risk for BRCA1 and BRCA2 mutation carriers at the age of 70 was, in different studies, reported to be between 36% and up to 71%." (PMID 21232165, 2011). "Among them we find breast cancer 2early onset gene 2 (BRCA2) which was expressed at significantly higher levels inthe mouse tumors." (PMID 21559450, 2011). "A total of 127 breast cancer patients were tested for BRCA1 and BRCA2 mutations using a combination of laboratory techniques." (PMID 22085629, 2011). "It has been estimated that tamoxifen reduces breast cancer risk in BRCA1-mutation carriers by 13% and in BRCA2-mutation carriers by 27%." (PMID 22312502, 2011). "BRCA1 and BRCA2 tumours have also been found to differ in terms of other tumour characteristics compared to breast cancers in the general population." (PMID 22053997, 2011). "The subsequent phase II study in 27 breast cancer patients with BRCA mutation (18 BRCA1 deficient and 9 BRCA2 deficient) showed RR of 41% and median PFS of 5.7 months." (PMID 21504625, 2011). "To complement the linkage approach, we evaluated the effect of common HMMR genetic variation on breast cancer risk in BRCA1 and BRCA2 mutation carriers." (PMID 22110403, 2011). "It has been estimated that between 5% and 10% of women diagnosed with breast cancer have a hereditary form of the disease, primarily caused by a BRCA1 or BRCA2 gene mutation." (PMID 21219598, 2011).
breast cancer (continued). "Family history of breast and ovarian cancer, besides breast cancer bilaterality, early-onset breast cancer and ethnicity, constitute the basic criteria for identifying cases affected by BRCA1 or BRCA2 mutations." (PMID 21989022, 2011). "About 5-10% of all breast cancers are estimated to be hereditary, and germline mutations in the tumor-suppressor genes BRCA1 (MIM#113705) and BRCA2 (MIM#600185) are found in a proportion of this group." (PMID 21989022, 2011). "Specific morphological characteristics of breast cancers are predictive of the presence of mutations in BRCA1 and BRCA2 which predispose to breast and ovarian cancers, particularly if they occur in women before the age of 40 years." (PMID 21352566, 2011). "Nevertheless, a low detection rate has also been perceived in another group of families with a single case of female breast cancer (Group E) where the mutation detection rates for BRCA1 and for BRCA2 were 8% and 0%, respectively." (PMID 21232165, 2011). "BRCA2 breast carcinomas tend to be ER+, PR+, Her2−, and higher grade than sporadic age-matched controls." (PMID 22295226, 2011). "DNA testing for breast cancer susceptibility became an option after the identification of the BRCA1 and BRCA2 genes." (PMID 20579331, 2010). "Data on the distribution of ER status for BRCA1 or BRCA2 breast cancer tumours were obtained from a study conducted by the BCLC." (PMID 20482762, 2010). "Relative activities of the forward and the reverse promoters of BRCA2 gene in different unsynchronized human breast cancer cells at 95% confluency." (PMID 20202217, 2010). "Analysis of breast cancer risk-associated SNPs identified by a large population-based GWA study of breast cancer has shown that several of these SNPs also appear to modify risk in BRCA1 and/or BRCA2 mutation carriers." (PMID 21114847, 2010). "BRCA2 related breast cancers are most often of luminal type and seem phenotypically harder to recognize." (PMID 20398395, 2010). "In the present study we investigated the association of these polymorphisms, tagged to genes demonstrated in vitro to be involved in irradiation response, with risk of breast cancer for BRCA1 and BRCA2 mutation carriers." (PMID 21114847, 2010). "Another gene with positive correlations is BRCA2 (Breast cancer 2, early onset), probe G_193736, with Pearson correlation of 0.8161 and Spearman correlation 0.7333)." (PMID 20805891, 2010). "Understanding the mechanisms of this stringent mechanism of BRCA2 gene expression regulation is critical to evaluate etiology of human breast cancer." (PMID 20202217, 2010). "PALB2 protein [OMIM #610355, a partner and localizer of BRCA2] was recently identified in a complex with BRCA2 (Breast Cancer 2) protein." (PMID 20122277, 2010). "A number of large studies, facilitated through the Consortium of Investigators of Modifiers of BRCA1/BRCA2 (CIMBA), have evaluated associations between genetic polymorphisms and breast cancer risk in BRCA1 and BRCA2 mutation carriers." (PMID 21114847, 2010). "DNA sequence data for BRCA1 and BRCA2 was obtained from 571 participants from the Australian Breast Cancer Family Study." (PMID 20807450, 2010). "We estimated that mutations in BRCA1 and BRCA2 explain 32% of breast cancer FRR for relatives of patients with ER-negative and 9.4% of the breast cancer FRR for relatives of patients with ER-positive disease." (PMID 20146796, 2010). "Mutation carriers have an increased life-time risk of developing breast cancer of 57% and 40% and of developing ovarian cancer of 40% and 18% for BRCA1 and BRCA2 respectively." (PMID 20398395, 2010). "The breast cancer predisposition genes BRCA1 and BRCA2 have been reported to increase the risk of PrCa by three-fold and seven-fold, respectively, in male mutation carriers ascertained through a family history of breast cancer." (PMID 20736950, 2010).
breast cancer (continued). "This approach would be similar to those that had pivotal roles in localising BRCA1 through using breast–ovary cancer families, and cloning BRCA2 through studying breast cancer families with male breast cancer." (PMID 20877337, 2010). "Next, we identified which of these CNAs occur both in mouse BRCA1- or BRCA2-deficient mammary tumors and in human BRCA1- or BRCA2-mutated tumors." (PMID 20735817, 2010). "To gain insight into the specific effects of BRCA1 or BRCA2 loss on genomic instability, we used aCGH profiles of genetically defined mouse models for BRCA1- and BRCA2-associated breast cancer as biological data filters to mine the human breast cancer genome." (PMID 20735817, 2010). "The discovery of breast cancer genes, BRCAl and BRCA2, has led to an explosive growth in cancer screening for population at risk." (PMID 20579331, 2010). "The major finding of the study is that only those loci known to be associated with breast cancer risk in the general population, including FGFR2 (rs2981575), modified BRCA2-associated risk in our high-risk population." (PMID 21060860, 2010). "The two most important genes that, when bearing a germline mutation, predispose to breast cancer, are the BRCA1 and BRCA2 genes." (PMID 20398395, 2010). "Identifying genes whose expression is associated with BRCA1, BRCA2 and BRCAX mutation status would be a valuable method of screening individuals from multiple case breast cancer families for the presence of pathogenic mutations." (PMID 20174566, 2010). "It possesses a functional and physical link with the gene product of BRCA2 (breast cancer 2, early onset)." (PMID 20334636, 2010). "Of the prevalent breast cancer patients screened for BRCA1 and BRCA2 mutations 519 had tumour pathology information." (PMID 20146796, 2010). "Sequencing data of exon 9 of BRCA2 gene which amplified from healthy woman (control) and patient with breast cancer, the alignment was carried out using Clustal W 1.9 program." (PMID 20579331, 2010). "We find that amplification of the MYC locus and the loss of the RB/INTS6 locus is evolutionarily conserved in mouse and human mammary tumor development, and that AURKA amplification is conserved in mouse and human BRCA2-mutated tumors." (PMID 20735817, 2010). "To analyze syntenic genomic regions for overlapping CNAs, we applied two statistical frameworks to BRCA1-deficient, BRCA2-deficient and BRCA1/2-proficient control mouse and human breast cancers: a total of six tumor groups." (PMID 20735817, 2010). "Fewer than 10% of breast cancers are attributable to known mutations in breast cancer susceptibility genes BRCA1 and BRCA2." (PMID 20111735, 2010). "Clinically, breast cancer is believed to begin at an earlier age in BRCA1 and BRCA2 gene mutation carriers compared with sporadic cases." (PMID 20961453, 2010). "We have reported previously that the transcriptional repressor protein SLUG negatively regulates BRCA2 gene expression in SLUG-positive breast cancer cells by binding to an E2-box flanked by two Alu sequences in the -701 to -921-bp region." (PMID 20202217, 2010). "Several mechanisms are known to be operative in breast cancer cells to regulate BRCA2 gene expression." (PMID 20202217, 2010).